PRKAR2A (protein kinase cAMP-dependent type II regulatory subunit alpha)
Diseases named in the same sentence as PRKAR2A in open-access papers (continued):
Sharing a sentence is not in itself a finding about the gene and the disease.
Vertigo (1 paper, 2022). An abnormal sensation of spinning while the body is actually stationary. "The poorly expressed circ_0000811, up-regulated miR-15b expression, and down-regulated Prkar2a expression were observed in both mice with CI-induced vertigo and OGD-exposed cells." (PMID 35508616, 2022). "Taken together, the data acquired in the present study elucidated the mechanism by which circ_0000811 overexpression ameliorated CI-induced vertigo through attenuating the apoptosis of neurons via the modulation of the miR-15b/Prkar2a/JAK2/STAT1 cascade." (PMID 35508616, 2022). "We then performed Western blot and validated the down-regulated protein level of Prkar2a in the MVN of mice with CI-induced vertigo as well as OGD-exposed cells." (PMID 35508616, 2022). "To substantiate the circ_0000811/miR-15b/Prkar2a/JAK2/STAT1 regulatory axis in vivo, we performed a series of gain- and loss- of functions assays on mice with experimental CI-induced vertigo." (PMID 35508616, 2022). "Furthermore, inactivation of the JAK2/STAT1 signaling pathway exerted an anti-apoptotic effect in OGD-induced neurons and an alleviatory effect in mice with CI-induced vertigo with Prkar2a overexpression and circ_0000811 overexpression." (PMID 35508616, 2022). "However, whether Prkar2a played a neuroprotective role in CI-induced vertigo through other downstream signal pathways remains unclear with further work required to deepen understanding." (PMID 35508616, 2022). "Circ_0000811 sponged miR-15b to inhibit its expression and augment Prkar2a expression, whereby the JAK2/STAT1 signaling pathway was repressed, and the apoptosis of neurons was thus attenuated to mitigate the CI-induced vertigo." (PMID 35508616, 2022). "Furthermore, our data revealed that Prkar2a inactivated the JAK2/STAT1 signaling pathway, thus attenuating neuronal apoptosis in CI-related vertigo." (PMID 35508616, 2022).
cancer (9 papers, 2015 to 2023). A tumor composed of atypical neoplastic, often pleomorphic cells that invade other tissues. "PRKAR2A codes for protein kinase A. Previous studies have shown that PRKAR2A deficiency predisposes patients to hematopoietic malignancies." (PMID 35096824, 2021). "These regulatory RNAs included the anti-sense RNAs HLA-F, LIFR, PRKAR2A, ZEB1, and long intergenic non-coding RNAs (LINC) 887, 1431, 2482, as well as microRNAs (MIRs) 22HG and 3648, which are associated with viral inflammation and cancer and cellular proliferation, respectively." (PMID 33763387, 2021). "In addition, PRKAR2A has been found to regulate the response of cancer cells to chemotherapy, which might be the reason why our established model helped predict the curative effect of neoadjuvant therapy in TNBC patients." (PMID 35096824, 2021). "A comprehensive review of the cancer genome atlas (TCGA) did not reveal PRKAR2A mutations in any human tumors but several studies show copy number changes of PRKAR2A’s chromosomal locus at 3p21 which, however, is gene-rich and is frequently lost in a variety of neoplasms." (PMID 26608815, 2015). "We found four paired lncRNA-mRNA exhibiting a substantially high SCNA frequency in cancers, including lncRNA FGD5-AS1 and PRKAR2A (KIRC, 44.2% and 44.4%), lncRNA TUG1 and CDC7 (LUAD, 25.9% and 23.6%), lncRNA TUG1 and DSC2 (LUAD, 25.9% and 26.1%) and lncRNA SNHG7 and PNMA2 (LUAD, 25.4% and 31.1%)." (PMID 32846981, 2020).
tumor (7 papers, 2014 to 2023). "Down-regulation of Prkar2a is associated with cell growth inhibition and tumor suppression." (PMID 24637697, 2014). "The PRKAR2A gene showed altered expression in an additional tumor (sample 14) with increase from exon 9 on." (PMID 28893231, 2017). "The major difference is that Prkar2a+/− and Prkar2a−/− mice develop with a high frequency hematopoietic neoplasms, particularly macrophage-derived HS tumors, as well as neoplasms derived from mature cells of the B cell lineage." (PMID 26608815, 2015). "Increased Prkar2a expression, related to a low-oxygen/high-altitude adaptation, was observed in the hearts of Tibetan pigs in comparison to low-land pigs, while the expression of Ppp1r1c has been studied only in tumor hypoxia." (PMID 38304737, 2023). "In addition, DCBLD2, CASP7, TSC22D1, ANXA7, PRKAR2A, ZMYND11, and PAK2 have been reported to be tightly linked to tumor malignancy in previous studies." (PMID 35513372, 2022). "Previous studies showed that Prkar2a knockout (KO) mice are viable, but a predisposition to tumor development has not been reported." (PMID 26608815, 2015).
gastrointestinal disease (1 paper, 2021). A disease that occurs in the gastrointestinal system, excluding the hepatobiliary system. "WT and Prkar2a−/− mice were subjected to DSS treatment, and they were monitored for clinical signs of gastrointestinal disease, such as weight loss, diarrhea, and rectal bleeding." (PMID 34349238, 2021).
hematologic malignancies (1 paper, 2015). "Cohorts of Prkar1a+/−, Prkar2a+/−, Prkar2a−/−, Prkar2b+/− and wild type (WT) mice have been observed between 5 and 25 months of age for the development of hematologic malignancies." (PMID 26608815, 2015). "We studied Prkar2a- haploinsufficient (Prkar2a+/−), Prkar2b- haploinsufficient (Prkar2b+/−), Prkar2a−/− KO, as well as double-heterozygote (Prkar1a+/−x Prkar2a+/-) F1 mice for the development of hematologic malignancies." (PMID 26608815, 2015).
hematopoietic neoplasms (1 paper, 2015). "Prkar2a-deficienct mice developed hematopoietic tumors with higher frequency than Prkar1a-deficient and WT mice." (PMID 26608815, 2015). "Prkar2a- deficiency, in particular, predisposes mice to a spectrum of mostly hematopoietic neoplasms, which may lead to better understanding of the molecular pathology of these lesions in both mice and humans." (PMID 26608815, 2015).
PRKAR2A also shares sentences with these, for which no sentence is quoted: Alzheimer disease (1 paper); Anxiety (1); cholangiocarcinoma (1); Crohn disease (1); gastric cancer (1); glioma (1); Huntington disease (1); Lewis body disease (1); Parkinsonism (1); schizophrenia (1); Splenomegaly (1).